PDE5A (phosphodiesterase 5A)
Diseases named in the same sentence as PDE5A in open-access papers (continued):
Sharing a sentence is not in itself a finding about the gene and the disease.
cardiac hypertrophy (23 papers, 2005 to 2025). "Severe cardiac hypertrophy caused systolic dysfunction similarly to moderate hypertrophy in Pde5a+/+ and Pde5a−/− mice." (PMID 40659490, 2025). "In accordance with this, inhibition of PDE-5A in rat myocardium probably underlies the cardioprotective effect of sildenafil against isoproterenol-induced cardiac hypertrophy observed in the present study." (PMID 15813973, 2005). "In addition, in vivo studies suggest that decreased miR-19a-3p expression could be associated with increased of cardiac hypertrophy by phosphodiesterase 5A (PDE5A) and myocyte enhancer factor 2 (MEF2) regulation." (PMID 34680526, 2021). "In Pde5a+/+ mice, an ∼25% increase in interstitial fibrosis was observed after severe hypertrophy versus 10% after moderate cardiac hypertrophy." (PMID 40659490, 2025). "Cardiac hypertrophy was surprisingly detected in Pde5a−/− mice after TAC surgery with similar alterations of cardiac function, morphology, fibrosis, and expression of molecular markers compared with Pde5a+/+ mice." (PMID 40659490, 2025). "The results revealed differences between pharmacological inhibition and genetic ablation targeting Pde5a in induced cardiac hypertrophy." (PMID 40659490, 2025). "To investigate this aspect and to clarify the role of Pde5a in cardiac hypertrophy induced by TAC, we used, for the first time, genetically modified mice deficient in Pde5a." (PMID 40659490, 2025). "We investigated Pde5a role in the development and progression of moderate and severe cardiac hypertrophy, induced by transverse aortic constriction (TAC), in Pde5a WT (Pde5a+/+) and Pde5a-deficient (Pde5a−/−) mice." (PMID 40659490, 2025). "This discovery will be very useful in term of personalized medicine because Pde5a inhibitors should be administrated depending on the severity of cardiac hypertrophy." (PMID 40659490, 2025). "As expected, the analysis showed that 26G TAC induced substantial chamber dilatation and development of moderate cardiac hypertrophy with reduced left ventricular systolic function in fractional shortening (FS%) and ejection fraction (EF%) in Pde5a+/+ mice." (PMID 40659490, 2025). "The Pde5a inhibitor, Sildenafil, prevented only moderate cardiac hypertrophy at the morpho-functional and molecular levels in Pde5a+/+ mice." (PMID 40659490, 2025). "Accumulation of cGMP in response to PDE5a inhibition counters the ill-effects of adrenergic stimulation and prevents cardiac hypertrophy and pressure-induced remodeling of the heart." (PMID 26709517, 2015). "Previous work reported that PDE5A was localized to Z-bands and that this localization was lost in advanced cardiac hypertrophy." (PMID 21151982, 2010). "In an attempt to examine other signaling pathways and other drugs, the present study probed the NO-cGMP pathway and the effect of its modulation by the selective PDE-5A inhibitor sildenafil in cardiac hypertrophy." (PMID 15813973, 2005). "Moreover, the Pde5a/Sildenafil system counteracts a metabolic rewiring occurring in cardiac hypertrophy." (PMID 40659490, 2025). "Sildenafil treatment prevented cardiac hypertrophy only in Pde5a+/+mice." (PMID 40659490, 2025). "Moreover, chronic inhibition of Pde5a by Sildenafil significantly attenuated cardiac hypertrophy and cardiac dysfunction induced by 26G TAC." (PMID 40659490, 2025). "However, both Pde5a+/+ and Pde5a−/− mice developed similar cardiac hypertrophy after moderate as well as after severe TAC-induced pressure overload." (PMID 40659490, 2025). "To better investigate this aspect and to clarify the role of Pde5a in cardiac hypertrophy induced by TAC, we used, for the first time, genetically modified mice deficient in Pde5a (Pde5a−/−) and we compared the responses with experimentally induced hypertrophy with or without Sildenafil." (PMID 40659490, 2025). "PDE5A is a leading factor contributing to cGMP signaling and cardiac hypertrophy." (PMID 32620106, 2020).
cardiac hypertrophy (continued). "For example, PDE5A likely regulates NO-derived cGMP and plays a critical role in mediating various types of cardiac diseases including ischemia/reperfusion (I/R) injury, doxorubicin cardiotoxicity, ischemic and diabetic cardiomyopathy, and cardiac hypertrophy." (PMID 29690591, 2018). "Consequently, PDE-5A inhibition by sildenafil and cellular accumulation of cGMP would be the braking force against isoproterenol-induced cardiac hypertrophy found in the present study." (PMID 15813973, 2005). "Thus, PDE9A inhibitors may have greater effectiveness than PDE5A inhibitors for treating cardiac hypertrophy when NO production is low." (PMID 37971403, 2024). "However, they might also oppose hypertrophy through the reduction of CTGF and PDE5A, and Ang II-induced attenuated levels of miR-19a/b could mediate cardiac hypertrophy." (PMID 33946230, 2021). "The relative mRNA expression of Bnp was greater than in moderate cardiac hypertrophy and 27G TAC was able to increase Bnp mRNA expression in Pde5a+/+ and Pde5a−/− mice, respectively." (PMID 40659490, 2025). "It was reported that the Pde5a inhibitor Sildenafil had cardioprotective effects, through protein kinase G (PKG) activation, in mouse heart hypertrophy, mainly in severe hypertrophy, that was induced by transverse aortic constriction (TAC)." (PMID 40659490, 2025). "Surprisingly, 26G TAC–induced cardiac hypertrophy with or without Sildenafil treatment was not prevented in Pde5a−/−." (PMID 40659490, 2025). "The first relevant result is that the lack of Pde5a does not protect from cardiac hypertrophy induction." (PMID 40659490, 2025). "Because the Pde5a−/− mice are surprisingly sensitive to moderate cardiac hypertrophy and it is not counteracted by Sildenafil, a more severe cardiac hypertrophy was induced." (PMID 40659490, 2025). "In our model of early cardiac hypertrophy, PDE5A localization to Z-bands was not affected by angiotensin II treatment." (PMID 21151982, 2010). "Herein, we show that NOS3 expression is not affected in early cardiac hypertrophy induced by angiotensin II and that PDE5A keeps a Z-band localization pattern." (PMID 21151982, 2010). "Genetic ablation of Pde5a does not protect against moderate/severe cardiac hypertrophy." (PMID 40659490, 2025). "It was interestingly shown that PDE5A was upregulated in different models of cardiac disease and that early correction of PDE5 alterations could restore heart function and prevent cardiac hypertrophy." (PMID 21151982, 2010). "Sildenafil treatment in vivo or administration of cGMP and Sildenafil, in vitro, induces an increase in the expression and activity of oxidative LDHB in Pde5a+/+ 27G TAC mice, that, however, is not sufficient to revert cardiac hypertrophy." (PMID 40659490, 2025). "Unlike PDE5A, PDE9A inhibition can reverse preestablished cardiac hypertrophy independent of NOS activity." (PMID 37971403, 2024).
prostate carcinoma (22 papers, 2009 to 2025). A carcinoma that arises from epithelial cells of the prostate gland. "A recent study showed that hsa_circ_0002474, one of the cyclic transcripts of PDE5A, is downregulated in prostate cancer tissues and inhibits prostate metastasis via the circPDE5A-WTAP-EIF3C-MAPK pathway." (PMID 38658954, 2024). "In addition, the use of the PDE5A inhibitors sildenafil or vardenafil enhanced apoptosis of human castration-resistant prostate cancer cells." (PMID 38762700, 2024).
Stroke (19 papers, 2011 to 2026). Sudden impairment of blood flow to a part of the brain due to occlusion or rupture of an artery to the brain. "The other 4 proteins (APOE, PDE5A, METAP1D, and TIMD4) were associated with either dementia or stroke with consistent effects as the MR analysis." (PMID 39818967, 2025). "PDE5A has been identified as a key target of anti-stroke traditional Chinese medicinal compounds." (PMID 37090981, 2023). "Most of candidate compounds and anti-stroke plants are tended to interact with target NOS3, PSD-95 and PDE5A." (PMID 28117389, 2017). "In all 192 anti-stroke plants, there are also many compounds which can interact with target NOS3, PDE5A, PSD-95." (PMID 28117389, 2017).
coronary artery disease (17 papers, 2017 to 2025). "As far as PDE5, a recent paper documented the identification of a PDE5A variant implicated in coronary artery disease." (PMID 36614143, 2022). "In addition to its effects on blood pressure, decreased PDE5A levels predicted increased coronary artery disease risk (β=0.15, P=1.60×10−7), consistent with the 25% increase in cardiovascular events observed in the trial." (PMID 41404285, 2025). "For coronary artery disease, another superfamily member (PDE5A) had a low ranking (<2%) by the GWAS and QTL-GWAS methods, supported by solid GWAS and e/pQTL colocalization." (PMID 37492104, 2023).
colon cancer (16 papers, 2013 to 2025). "The literature describes PDE5A as overexpressed in breast and colon tumor cells while the expression of other cGMP PDE isozymes is decreased." (PMID 27927168, 2016). "PDE5A also belongs to a protective factor for the prognosis of colon cancer." (PMID 37280069, 2023).
ischemia (14 papers, 2005 to 2025). A hypoperfusion of the BLOOD through an organ or tissue caused by a PATHOLOGIC CONSTRICTION or obstruction of its BLOOD VESSELS, or an absence of BLOOD CIRCULATION. "Previous studies have shown that inhibition of PDE-5A in the myocardium enhanced coronary blood flow during exercise-induced ischemia, blunted cardiac stimulation by dobutamine and reduced contractility of adrenergically stimulated papillary muscle." (PMID 15813973, 2005). "Moreover, PDE5A was demonstrated to promote endothelial proliferation, migration, and capillary-like tube formation during ischemia of the mouse hind limb." (PMID 35822023, 2021).
colorectal cancer (13 papers, 2016 to 2025). A primary or metastatic malignant neoplasm that affects the colon or rectum. "In colorectal cancer, the use of PDE5A inhibitors had been found to be associated with a favorable prognosis and lower metastasis rate in male with colorectal cancer." (PMID 38762700, 2024). "Three proteins identified by MR, S100A16, S100A14 and PDE5A, might share causal variables with HER-positive breast cancer and colorectal cancer." (PMID 38762700, 2024). "Moreover, PDE5A were regarded as first-class target of colorectal cancer." (PMID 38762700, 2024). "Interestingly, the results of colocalization analysis showed that S100A16 (coloc, PP.H4.abf = 0.933), S100A14 (coloc, PP.H4.abf = 0.913), and PDE5A (coloc, PP.H4.abf = 0.855) had the shared causal variation with HER-positive breast and colorectal cancers, respectively." (PMID 38762700, 2024). "Ultimately, based on our analysis, S100A16 and S100A14 were validated as potential second-class drug targets for HER-positive breast cancer, PDE5A as potential first-class drug targets for colorectal cancer, and MIA as potential second-class drug targets for non-small cell lung cancer." (PMID 38762700, 2024).
cognitive deficits (12 papers, 2013 to 2026). "In addition, ICS II protected against cognitive deficits may be closely interrelated to inhibition of PDE5A protein." (PMID 28337142, 2017).
COVID-19 (12 papers, 2020 to 2025). A disease caused by infection with severe acute respiratory syndrome coronavirus 2. "We found that PDE5A, ITGB3, CEACAM8, and BPI were hub-shared genes in IS and COVID-19, which were remarkably enriched in pathways such as ECM-receptor interaction and focal adhesion pathways." (PMID 37090981, 2023).
lung carcinoma (10 papers, 2014 to 2024). "Consistent with the transcriptome data, SERPINE2 was more highly expressed in lung cancer tissues compared with that in paratumor tissues, while a low expression of FGF10, LSAMP, and PDE5A was found in lung cancer tissue." (PMID 37280069, 2023).
pulmonary fibrosis (10 papers, 2009 to 2024). Chronic progressive interstitial lung disorder characterized by the replacement of the lung tissue by connective tissue, leading to progressive dyspnea, respiratory failure, or right heart failure. "In contrast to our findings that EGCG upregulated PDE5A expression in IPF fibroblasts, PDE5A inhibition by sildenafil improved bleomycin-induced pulmonary fibrosis by reducing oxidative stress." (PMID 31013581, 2019).
congestive heart failure (9 papers, 2011 to 2024). Failure of the heart to pump a sufficient amount of blood to meet the needs of the body tissues, resulting in tissue congestion and edema. "The aim of the study was to determine the impact of selected angiotensin converting enzyme (ACE) and PDE5A polymorphisms on presence of congestive heart failure (CHF) due to MMVD in Cavalier King Charles Spaniels (CKCS)." (PMID 38053473, 2023).
breast tumors (7 papers, 2010 to 2024). "The capability of STGIC is validated indirectly by expression of marker genes of invasive breast tumor in the predicted spatial domains, which are C6orf141, PDE5A, LINC00645, BMERB1, ABCC11, ABCC12." (PMID 38416785, 2024).
dementia (7 papers, 2022 to 2025). Loss of intellectual abilities interfering with an individual's social and occupational functions. "The TBI‐associated dementia‐related increase in PDE expression is unique to PDE11A in that PDE2A, PDE5A, and PDE10A expression remained unchanged." (PMID 36073342, 2022). "Finally, the lack of bidirectional evidence, in which dementia is causally linked with PDE5A protein levels, further suggests robustness against reverse causality." (PMID 39951190, 2025).
fibrosis (6 papers, 2013 to 2025). the formation of excess fibrous connective tissue in an organ or tissue in a reparative or reactive process. "This is the first study to demonstrate that the use of a PDE5A inhibitor leads to functional improvement in burn-induced cardiac dysfunction, and that cardiac fibrosis, inflammation and oxidative stress can be mitigated as well." (PMID 32503314, 2020).
cardiomyopathy (5 papers, 2013 to 2024). A disease of the heart muscle or myocardium proper. "In addition, inhibition of TNNI3K or PDE5A was shown to be cardioprotective against several cardiomyopathies." (PMID 35172813, 2022).
migraine (5 papers, 2014 to 2025). "PDE5A activation could be important in reversal of migraine-like headache." (PMID 25247292, 2014).
Headache (4 papers, 2014 to 2018). Cephalgia, or pain sensed in various parts of the head, not confined to the area of distribution of any nerve. "In addition, several other genes were significantly upregulated, including genes associated with neuronal survival (PDE5A) and certain classes of migraine headaches (ATP1A2)." (PMID 25337697, 2014). "PDE5A is thought to have particular relevance to migraine headache pathophysiology and to possibly play a central role in the trigeminovascular system." (PMID 25247292, 2014). "Inhibition of PDE5A induces headache resembling migraine headaches." (PMID 25247292, 2014).
Huntington disease (4 papers, 2024 to 2025). Huntington disease (HD) is a rare neurodegenerative disorder of the central nervous system characterized by unwanted choreatic movements, behavioral and psychiatric disturbances and dementia. "Enrichment analyses showed that PDE5A was clearly involved in ‘ECM receptor interaction’, ‘Parkinson’s disease’, ‘peroxisome’, ‘Huntington’s disease’ and ‘oxidative phosphorylation’." (PMID 38332893, 2024).
bladder cancer (3 papers, 2021 to 2025). "We further investigated these genes using the Oncomine database, and the results also indicated lower expression of PDE5A, RECK, ZEB2, and CYBRD1 in bladder cancer tissue than in normal bladder mucosa." (PMID 33987019, 2021). "Further analysis of gene expression from the GEO dataset indicated lower expression of PDE5A, RECK, ZEB2, and CYBRD1 in bladder cancer tissue than in normal bladder mucosa, which indicated that PDE5A, RECK, ZEB2, and CYBRD1 may act as tumor suppressors in UTUC." (PMID 33987019, 2021).
emphysema (3 papers, 2015 to 2024). "miR-31-3p might have a protective role via decreasing PDE5A expression and thus smoke-induced emphysema." (PMID 35379844, 2022).
esophageal squamous cell carcinoma (3 papers, 2022 to 2025). Esophageal squamous cell carcinoma (ESCC) is a type of esophageal carcinoma (EC) that can affect any part of the esophagus, but is usually located in the upper or middle third. "The novel protein PDE5A-500aa encoded by circPDE5A can act as an inhibitor of the PI3K/AKT signaling pathway to inhibit the progression of esophageal squamous cell carcinoma." (PMID 38658954, 2024). "PDE5A‐500aa was identified as a specific polypeptide in esophageal squamous cell carcinoma (ESCC), suppressing the expansion and metastasis of ESCC cells." (PMID 40717901, 2025).
muscular dystrophy (3 papers, 2007 to 2022). Muscular dystrophy (MD) refers to a group of more than 30 genetic diseases characterized by progressive weakness and degeneration of the skeletal muscles that control movement. "In our previous study, we demonstrated that PDE5A inhibition could ameliorate muscular dystrophy by acting at different levels, as assessed by the altered genomic response of muscular cells following treatment with the PDE5A inhibitor tadalafil." (PMID 36614143, 2022).
neuroblastoma (2 papers, 2014 to 2017). Neuroblastoma (NB) is the most common solid, extracranial childhood tumor. "Wild type PDE5A or PDE5A with substitution mutations (Ser102Ala, Ser104Ala or Ser102Ala/Ser104Ala) were overexpressed in SK-N-AS neuroblastoma cells as C-terminal fusions with green fluorescent protein." (PMID 25247292, 2014).
thoracic aortic aneurysm (2 papers, 2019 to 2021). An aneurysm formed in the wall of the proximal portion of the descending aorta proceeding from the arch of the aorta. "Upregulation of PDE5A expression in smooth muscle cells induced by angiotensin II decreases cGMP signaling, contributing to vasoconstriction while downregulation of PDE5A is associated with human thoracic aortic aneurysms." (PMID 35822023, 2021).
vascular dementia (2 papers, 2023 to 2025). A degenerative vascular disorder affecting the brain. "Similarly, circulating levels of PDE5A were not affected by genetic liability to Lewy body dementia (β 0.004, 95% CI − 0.007, 0.015, p = 0.428) or vascular dementia (β 0.002, 95% CI –0.012, 0.016, p = 0.79)." (PMID 39951190, 2025).
adrenocortical tumors (1 paper, 2020). "In the present work, when the transcriptome analysis was accessed, a decrease of PDE2A, PDE5A, and PDE8A expression and a significant overexpression of PDE4B and PDE8B was observed in adrenocortical tumors, compared to normal adrenal tissue." (PMID 32098292, 2020).
advanced heart failure (1 paper, 2022). Patients with advanced heart failure have severe limitations, experiences symptoms even while at rest and are mostly bedbound patients. "Phosphodiesterase-5a inhibition (PDE5i) leads to favorable changes in pulmonary hemodynamic and cardiac output (CO) in patients with advanced heart failure (HF) and reduced ejection fraction (HFrEF)." (PMID 35722098, 2022).
dystrophin deficiency (1 paper, 2016). "The aggregate results from our study imply that treatment of neurobehavioral symptoms associated with developmental disturbances stemming from dystrophin deficiency and impaired cGMP signaling in the cerebellum may be improved by using either a PDE9A specific inhibitor or a PDE5A inhibitor." (PMID 27676442, 2016).
hepatoblastoma (1 paper, 2024). Hepatoblastoma (HB) is a malignant hepatic tumor and is the most common pediatric liver cancer. "Hepatoblastoma tumor cells exhibited upregulation of purine metabolism through enhanced expression of ENTPD1, PDE4C, PDE5A, and PAPSS1." (PMID 39684755, 2024).